PPARG (peroxisome proliferator activated receptor gamma)
Diseases named in the same sentence as PPARG in open-access papers (continued):
Sharing a sentence is not in itself a finding about the gene and the disease.
Obesity (continued). "PPARγ is an important transcription factor in mammalian adipogenesis and is closely related to obesity." (PMID 33322515, 2020). "PPARγ activators are commonly used in the treatment of diabetes and obesity since PPARγ is involved in lipid biosynthesis and adipogenesis regulation." (PMID 32470015, 2020). "In obesity, phosphorylation of PPARγ on the Ser273 residue by CDK5 leads to dysregulation of a specific gene set." (PMID 32024237, 2020). "Because many known obesogens activate PPARγ and induce adipogenesis, PPARγ activation is widely believed to be a major mechanism through which obesogens can contribute to obesity." (PMID 32067051, 2020). "Our study suggests low-energy shockwave treatment as a way to modulate a Wnt10b/β-catenin pathway and PPARγ expression, and provides new insights for the treatment of obesity." (PMID 31936603, 2020). "A recent study suggested that SC suppresses obesity in high-fat diet-induced obese rats and 3T3-L1 cells by decreasing expression of C/EBPα and PPARγ." (PMID 32245100, 2020). "Previous research has focused on the development of β3-AR agonists or PPARγ agonists to treat metabolic disorders including obesity." (PMID 32351446, 2020). "Protein levels of PTEN are induced by activation of peroxisome proliferator-activated receptor gamma (PPARγ) which mediates the interplay between cancer and metabolic syndromes, diabetes, and obesity." (PMID 32708484, 2020). "PPARG is known to affect obesity, adipose and muscle tissue metabolism, and craniofacial abnormalities thereby causing OSA." (PMID 31044373, 2020). "Fucoxanthinol and amarouciaxanthin accentuates these anti-obesity actions of fucoxanthin in later stages of adipocyte differentiation by suppressing PPARγ expression and glucose uptake." (PMID 32903449, 2020). "Previous studies have reported an increase in PPARγ expression by obesity in adipose tissue in an animal model and in humans, perhaps reflecting an attempt of the increasing adiposity to maintain insulin sensitivity." (PMID 32731460, 2020). "PPARγ is primarily expressed in adipose tissue, colon and immune system and takes part in distinct diseases including obesity, diabetes, atherosclerosis and cancer." (PMID 32500465, 2020). "Inhibition of PPARγ by an antagonist prevented high fat diet (HFD)-induced obesity and improved glucose and lipid metabolism." (PMID 31936603, 2020). "A number of genes have been shown to be involved in the development of obesity, including peroxisome proliferator-activated receptor γ (PPARγ), CCAAT/enhancer-binding protein α (C/EBPα), and sterol regulatory element-binding protein 1c (SREBP1c)." (PMID 33313321, 2020). "MiR-130 expression was downregulated in scAT of patients with obesity compared to controls, and, accordingly, PPARG mRNA expression was upregulated." (PMID 33207733, 2020). "When obesity was induced by a high-fat diet, CDK5 and its associated PPARγ phosphorylation were upregulated in vivo, which led to impaired insulin sensitivity." (PMID 32054125, 2020). "Depletion of β-catenin and PPARγ in VAT cDCs stimulates a pro-inflammatory response in a mouse model of obesity, suggesting a role of these pathways in cDCs in delaying the onset of metabolic disease." (PMID 32499756, 2020). "In laboratory research, we found that the traditional Chinese herb Sibiraea angustata (SA) can inhibit cell differentiation and lipogenesis by regulating the expression of PPARγ and other genes in 3T3-L1 preadipocytes to manage obesity." (PMID 31336903, 2019). "PPARγ dysregulation has been reported in several disorders characterized by over-activation of inflammatory response, including obesity, diabetes, atherosclerosis, and cancer." (PMID 30934838, 2019). "Our findings imply that HSPA12A is a novel regulator of adipocyte differentiation and diet-induced obesity through a positive feedback regulation with PPARγ." (PMID 30742088, 2019).
Obesity (continued). "The obesity‐induced hypotriglyceridemia and changes in hepatic PPARγ, skeletal muscle FAS, and white adipose tissue FATP1 and FAS are similar to that observed for pregnant rodents fed an obesogenic diet during pregnancy alone." (PMID 31466137, 2019). "Previous studies demonstrated that BR is a potential candidate for treating obesity via a negative regulation of PPARγ and C/EBPα in 3T3-L1 adipocytes." (PMID 31509935, 2019). "As mentioned in introduction, PPARγ has been identified as a therapeutic target for obesity, hyperlipidaemia and diabetes for the dual functions of regulating glycolipid metabolism and inhibiting inflammation." (PMID 30873215, 2019). "Hydroxychloroquine shows potential in ameliorating obesity-induced pathology, which acts though PPARγ to facilitate the healthy function of hepatic tissues." (PMID 31427967, 2019). "It was proven that Dec1KO mice suppressed inflammation in periodontitis and obesity by decreasing inflammatory factors such as TNFα, IL-1β, and peroxisome proliferative active receptor gamma (PPARγ)." (PMID 31597354, 2019). "This study mainly focused on the effects of the dysregulated expression of peroxisome proliferator-activated receptor gamma (PPAR-γ) in obesity." (PMID 31007685, 2019). "Accordingly, myeloid-specific deletion of PPARγ exacerbates macrophage inflammation and promotes the development of diet-induced obesity." (PMID 31191541, 2019). "In support of this, inhibition of PPARγ by antagonists ameliorates high-fat diet (HFD)-induced obesity and impairments of glucose and lipid homeostasis." (PMID 30742088, 2019). "This phenomenon is generally seen in adult obesity, which is hypertrophic in nature and the reason why PPARγ agonists such as thiazolidinediones (TZDs) are useful in treating obesity." (PMID 31182642, 2019). "It has been reported that in obesity, phosphorylation of PPARγ at serine 273 stimulates diabetogenic gene expression in adipose tissues." (PMID 31226166, 2019). "More importantly, our results demonstrated that PCB2 ameliorated obesity-related inflammation via a PPARγ-dependent up-regulation of Ym1, Arg1, and Fizz1." (PMID 31440258, 2019). "The purpose of the study was to address the role of PPARγ in VSMCs in a model of high fat-diet (HFD) induced obesity." (PMID 30813929, 2019). "In our previous study, DBZ inhibited HFD-induced obesity in mice by selectively activating PPARγ to a significant level and PPARα to a moderate level, but it did not activate PPARβ/δ." (PMID 31336903, 2019). "PPARγ gene acts as a regulator of adipocyte differentiation and is involved in multiple diseases such as obesity, diabetes, atherosclerosis, and cancer." (PMID 31816986, 2019). "Ffar4, known as GPR120, promotes adipogenesis via PPARγ but also attenuates low-grade inflammation and insulin resistance accompanying obesity." (PMID 31208033, 2019). "Peroxisome proliferator-activated receptor γ (PPARγ) plays the master role in adipocyte differentiation for obesity development." (PMID 30742088, 2019). "Peroxisome Proliferator-Activated Receptor γ (PPARγ) is an important sensor at the crossroad of diabetes, obesity, immunity and cancer as it regulates adipogenesis, metabolism, inflammation and proliferation." (PMID 30931956, 2019). "This evidence shows that hydroxychloroquine plays a role in improving obesity-induced lipotoxicity and insulin resistance though the peroxisome proliferator-activated receptor gamma pathway." (PMID 31427967, 2019). "Lastly, we explore the potential of PPARγ as a druggable target to decrease adiposity, increase bone density, and be a treatment for children with obesity-induced bone fractures." (PMID 31798753, 2019). "Methylation of several gene promoters, such as HAND2, HOXC6, and PPARG, influences adipogenesis and differentiation, obesity, lipid metabolism, and adipose tissue expandability." (PMID 30911298, 2019). "Given that PPARG is an essential regulator of adipogenesis, it has been the target of anti-obesity research." (PMID 29541908, 2019).
Obesity (continued). "SIRT1, an NAD+-dependent deacetylase, impaired adipogenesis by directly acting as a PPARG co-repressor, thus, counteracting obesity." (PMID 29541908, 2019). "Next, relationships between serum adiponectin/leptin (A/L) ratio and clinical parameters were evaluated because adiponectin and leptin show vastly different serum concentrations in obesity and opposite effects on PPARγ expression." (PMID 31324858, 2019). "PPARγ in VSMCs is supposed to play a critical role in PAH-associated pulmonary remodelling, in addition to obesity-related pulmonary hypertension." (PMID 30813929, 2019). "PPARγ regulates lipogenic and adipogenic gene expression and is related to the pathophysiology of obesity." (PMID 31827150, 2019). "In the obesity model, PPARγ, C/EBPα, STREBP-1c, ACC, FABP4, FAS, and HSL were increased while PLIN was decreased in WAT." (PMID 31533255, 2019). "It was reported that PPARG is a regulator of adipocyte differentiation, energy homeostasis and obesity." (PMID 30838172, 2019). "It is well documented that PPARγ is critical in regulating inflammation by targeting adipose tissue Treg cells in obesity." (PMID 31191541, 2019). "Collectively, these results demonstrate that cDC-specific deletion of β-catenin and PPARγ enhances local inflammatory responses and aggravates obesity-induced insulin resistance." (PMID 29514067, 2018). "Taken together, PPARγ signaling in the brain seems to profoundly impact energy balance and to promote the obesity phenotype." (PMID 29997323, 2018). "Briefly, in HFD induced obesity, protein kinase cyclin-dependent kinase 5 (Cdk5) is activated and in turn phosphorylates PPARγ at Ser273." (PMID 30186237, 2018). "PPARγ upregulation of SCD1 leads to increased lipogenesis and elevated levels of SCD1 is associated with obesity." (PMID 30248999, 2018). "Obesity occurs through an increase in the number and size of adipocytes with the excessive accumulation of triacylglycerols; therefore, a PPARγ-mediated increase in adipocytes enhances obesity." (PMID 29757949, 2018). "Hepatic PPARγ, which is upregulated in obesity, stimulates expression of lipid droplet proteins as well as fatty acid transporters, thereby promoting liver steatosis." (PMID 30013137, 2018). "In concert with the data obtained in our rodent models of obesity and insulin resistance, adipose tissue expression of other lipogenic genes, including PPARG, FASN, and SLC2A4, was lower in subjects with MAO than those with MNO." (PMID 29853530, 2018). "Previous research has indicated that butyrate supplementation upregulates PPARγ expression in pig adipocytes and prevents diet-induced obesity by increasing energy expenditures." (PMID 30428630, 2018). "Peroxisome proliferator−activated receptor-gamma (PPARG) is another gene that has an important role in obesity." (PMID 29679223, 2018). "Taken together, our results indicate that Grail plays a pivotal role in adipogenesis and diet-induced obesity by regulating PPARγ activity." (PMID 29743578, 2018). "Knocking out PPARγ in adipose tissue of mice can prevent high-fat diet-induced obesity and insulin resistance." (PMID 30034368, 2018). "The transcriptome changes of VAT Treg cells provoked by obesity were thought to be mediated by activation of Cdk5, which deactivated PPARγ through phosphorylation of serine residue 273 (Ser273]." (PMID 30323806, 2018). "Studies have reported that elevated PPARγ expression level were observed in the liver of mice models of diabetes or obesity, such as in KK-Ay mice, ob/ob mice and db/db mice, all of which developed severe hepatic steatosis." (PMID 30061831, 2018).
Obesity (continued). "In our recently study, DBZ, as a promising therapeutic agent for atherogenesis and obesity in the mouse models, inhibits inflammation, macrophage migration, and foam cell formation, possibly through the partial activation of both PPARγ and LXRs." (PMID 29690611, 2018). "DBZ also activates PPARγ and prevents high fat diet-induced obesity, insulin resistance and gut dysbiosis in mice." (PMID 29690611, 2018). "TZDs, the pharmacological agonists of PPARγ, have been used clinically as antidiabetic agents, and their beneficial effects are well documented in relation with insulin resistance and obesity." (PMID 30037087, 2018). "Intriguingly, the transcriptional signature of obese VAT Treg cells was also dependent on PPARγ's phosphorylation of the serine residue at position 273, which was provoked by obesity." (PMID 30323806, 2018). "In recently study, we reported that DBZ prevented high fat diet-induced obesity and related metabolic disorders and attenuated atherosclerosis through concurrent partial activation of both PPARγ and LXRs." (PMID 29690611, 2018). "Nobiletin can improve obesity and insulin resistance in rats fed a high-fat diet by increasing PPARγ expression or regulating NF-κB and Nrf2 pathways." (PMID 30327679, 2018). "In fact, several studies have reported interactions between PPARG and environmental factors such as gender, dietary fat intake, or breast feeding on obesity traits." (PMID 29795275, 2018). "Studies have shown that butyrate production can influence metabolism by epigenetically regulating obesity-related gene expressions such as PPARγ and interferon-γ." (PMID 30210530, 2018). "We should further elucidate the mechanism by which orientin suppresses Dex-activated PPARγ expression and conduct an in vivo study to evaluate the anti-obesity properties of orientin." (PMID 29373533, 2018). "For Instance, SRC-1−/− mice showed partially impaired PPARγ function in the brown fat and are prone to obesity due to reduced energy expenditure and fatty acid oxidation upon HFD feeding." (PMID 30186237, 2018). "In contrast, SRC-1 which is robustly recruited to PPARγ through lesinurad binding has been associated with the regulation of energy homeostasis in adipose tissue and SRC-1 knockout in mice favored obesity development." (PMID 30202096, 2018). "PPARγ down-regulation and reduced genomic occupancy was previously observed in models of obesity and diabetes." (PMID 29656108, 2018). "In this regard, PPARγ was suggested as a molecule linking external or systemic factors (such as diet or obesity) and specific intra-cellular factors (such as the p16 gene) to control cellular senescence." (PMID 30307152, 2018). "BMP-3b also increases energy expenditure and protects high-fat diet-induced obesity by suppressing peroxisome proliferator-activated receptor γ (PPARγ)." (PMID 29922215, 2018). "Although SNPs were located on obesity-related genes, some of the genes also have a direct role in lipid metabolism including PPARG, FABP2, PLIN1, NPC1, ACSL5, and FAAH, suggesting relationships between genetics, adiposity, and plasma lipid profiles." (PMID 30581838, 2018). "PPARG (ENSP00000287820), a specific steroid hormone coactivator, has also been reported to participate in obesity-associated biological processes." (PMID 29258237, 2017). "The aim of this study was to investigate the association of four single nucleotide polymorphisms (SNPs) of peroxisome proliferator-activated receptor gamma (PPARG) with type 2 diabetes mellitus (T2DM) risk and additional role of gene-obesity interaction." (PMID 28123453, 2017). "In mammals, it has been demonstrated that CA and HT exhibit a significant potential to act as anti-obesity agents by modulating the PPARγ adipogenesis pathway." (PMID 28570659, 2017). "Because of the clinical and pathological implications in obesity, diabetes, inflammation, and cancer, PPARγ agonists have been developed in an attempt to treat these diseases." (PMID 28059128, 2017).
Obesity (continued). "In the Center for the Health Assessment of Mothers and Children of Salinas (CHAMACOS) cohort, we have previously examined a subset of PPARγ CpG sites and their relationship with gene expression in a cohort of children with a high prevalence of obesity." (PMID 28122515, 2017). "In the current study, there was a highly significant association between the elevated levels of miR-130b and the decreased levels of PPARγ in cases of obesity and CRC acquisition." (PMID 28878369, 2017). "PPARγ in macrophages plays a protective role against the development of inflammatory diseases, such as atherosclerosis, obesity, and colitis." (PMID 29057966, 2017). "We also studied the methylation pattern of PPARγ gene promoter and how it affected PPARγ production in obesity and CRC." (PMID 28878369, 2017). "Together, our data demonstrate that RORα controls PPARγ signaling to protect against hepatic metabolic homeostasis and obesity in response to HFD." (PMID 28757615, 2017). "Peroxisome-proliferator-activated receptors (PPARs) are the nuclear hormone receptor including PPARα, PPARδ, and PPARγ, which play a critical role in regulation of obesity, cardiovascular diseases, and inflammation." (PMID 28293264, 2017). "It has been shown that moderate reduction of PPARγ activity in mice prevented the insulin resistance and obesity induced by a high-fat diet." (PMID 28464894, 2017). "An intriguing observation in this study is that RORα is crucial to recruit HDAC3 to repress hepatic PPARγ-mediated lipogenic genes and protect against diet-induced hepatic steatosis and obesity." (PMID 28757615, 2017). "It is well-documented that CL316,243 (a β3 agonist) or rosiglitazone (a PPARγ agonist) can induce white adipocyte populations to brown-like adipocytes, thus increasing energy consumption and combating obesity." (PMID 28481288, 2017). "This study is, to our knowledge, the first to report that Lrp1 is a co-activator of Pparγ and that depletion of Lrp1 in endothelium regulates global energy homeostasis and alleviates some metabolic syndromes, such as obesity and insulin resistance." (PMID 28393867, 2017). "Elevated plasma FFA, an exogenous ligand for PPARγ, can activate PPARγ through direct interaction with the ligand-binding domain during obesity." (PMID 29176994, 2017). "In the current investigation, we build on this finding and add to current data gaps on PPARγ methylation and its relationship with obesity." (PMID 28122515, 2017). "We find that ZIP14 expression is reduced in obesity and positively correlates with PPARG expression, which is downregulated with increasing BMI." (PMID 28303117, 2017). "Our data confirm that RORα is a key factor for the repression of PPARγ signaling to protect against diet-induced hepatic steatosis and obesity in vivo." (PMID 28757615, 2017). "Effects of PPARγ activation by glitazones in relation to obesity and cardiovascular disease have been reported." (PMID 28656106, 2017). "Dysregulated PPARγ signaling in RORαLKO mice results in uncontrolled lipogenesis, contributing to the development of hepatic steatosis and diet-induced obesity on a HFD." (PMID 28757615, 2017). "Peroxisome proliferator-activated receptor gamma (PPARγ) is a nuclear receptor that is deregulated in obesity." (PMID 28878369, 2017). "Natural products, which have shown large potential to regulate PPARγ expression and/or transcriptional activity, are potential therapies to suppress adipogenesis and, thereby, fight against obesity." (PMID 27669202, 2016). "PPARγ deficiency in the livers of ob/ob mice and mice with HFD-induced obesity dramatically improves hepatic steatosis." (PMID 26770990, 2016). "Westudied a possible association of polymorphisms FTO rs9939609,PPARG rs1801282, and ADIPOQ rs4632532 andrs182052 with obesity phenotypes in 215 Mexican children." (PMID 27560839, 2016).